SAG (S-antigen visual arrestin)
Diseases named in the same sentence as SAG in open-access papers (continued):
Sharing a sentence is not in itself a finding about the gene and the disease.
night blindness (5 papers, 2012 to 2025). Inability to see clearly in dim light. "For instance, in mouse models in which the SAG gene (which encodes Arrestin-1) is mutated or Arrestin-1 function is compromised, photoresponse is not properly inhibited and the retina is incapable of adequate dark adaptation, which can lead to night blindness." (PMID 36766830, 2023). "Missense mutations that are not the target of NMD may remain some basic function of the SAG protein and therefore cause mild Oguchi’s disease without significant night blindness." (PMID 22419846, 2012).
prostate carcinoma (5 papers, 2016 to 2025). A carcinoma that arises from epithelial cells of the prostate gland. "In PTEN-deficient prostate cancer mouse models, SAG deletion suppresses the abnormal activation of PI3K/AKT/mTOR signaling." (PMID 41343534, 2025). "Since we have previously shown that SAG knockdown causes DEPTOR accumulation to block mTORC signaling in prostate cancer cells, we focused our study on CDH1." (PMID 36548081, 2023). "To gain mechanistic insight into SAG action, we used the loss-of-function approach in two human prostate cancer cell lines and found that SiRNA-based SAG knockdown caused in general accumulation of PHLPP1 and DEPTOR with consequential inactivation of pAKT and mTORC1 activity." (PMID 27955654, 2016). "Consistently, SAG knockdown suppressed the growth and survival of human prostate cancer cells due to accumulation of PHLPP1 and DEPTOR, two new substrates of SAG E3 ligase, which can be partially rescued by simultaneous knockdown of PHLPP1 or DEPTOR." (PMID 27955654, 2016). "SAG is overexpressed progressively from early-to-late stage of human prostate cancer with the highest expression seen in metastatic lesion." (PMID 27955654, 2016). "The effect of SAG knockdown in proliferation, survival and migration was evaluated in two prostate cancer cell lines." (PMID 27955654, 2016). "This notion was further supported by our rescued experiment in which simultaneous knockdown of either PHLPP1 or DEPTOR largely abrogated the growth suppression triggered by SAG knockdown in DU145 prostate cancer cells." (PMID 27955654, 2016). "SAG knockdown in human prostate cancer cells inhibits a) proliferation in monolayer and soft agar, b) clonogenic survival, and c) migration." (PMID 27955654, 2016). "Furthermore, SAG knockdown also significantly inhibited migration of human prostate cancer cells." (PMID 27955654, 2016). "Collectively, our results suggested that SAG knockdown triggers accumulation of PHLPP1 and DEPTOR to inactivate the AKT/mTOR axis, leading to observed suppression of growth and survival in prostate cancer cells." (PMID 27955654, 2016). "It is also worth noting that the effect of SAG knockdown appears not to be compensated by RBX1 in prostate cancer cells." (PMID 27955654, 2016). "Interestingly, the accumulation of CRL substrates induced by SAG knockdown was rather selective, since other two SCF/CRL1 substrates p21 and p27, two CRL5 substrates FLNA and DAB1, and one CRL3 substrate NRF2 were not accumulated in these two lines of prostate cancer cells upon SAG depletion." (PMID 27955654, 2016).
medulloblastoma (4 papers, 2009 to 2022). A malignant, invasive embryonal neoplasm arising from the cerebellum. "Some individual members of these pathways, including GNB3, GNB5, GABRA5, RCVRN and SAG were exclusively over-expressed in Group 3 medulloblastoma." (PMID 25412507, 2014). "In addition, SAG (Shh signaling pathway agonist) antagonized the pro-apoptotic effects of BDDD-721 on medulloblastomas as confirmed by CCK8 assays and flow cytometry; while cyclopamine (Shh signaling pathway inhibitor) enhanced its effects on medulloblastomas." (PMID 35802536, 2022). "Furthermore, and in line with the proliferative role of HH/GLI in medulloblastoma, 4SC‐202 treatment also reduced the growth of SAG‐stimulated Daoy cells." (PMID 29055107, 2018). "However, combination of 0.6 μM SAG and 20 μM BDDD-721 partially rescued BDDD-721-induced inhibition of medulloblastoma cell growth in both DAOY and ONS-76 cells." (PMID 35802536, 2022).
retinal disease (4 papers, 2007 to 2017). "Because the SAG gene product serves to turn off activated rhodopsin during the phototransduction cascade, it may be that the “toxic molecule” in SAG associated retinal disease is the activated but unquenched opsin apoprotein." (PMID 24019744, 2013).
autoimmune disease (3 papers, 2017 to 2025). A disorder resulting from loss of function or tissue destruction of an organ or multiple organs, arising from humoral or cellular immune responses of the individual to their own tissue constituents. "We hypothesized that further component analysis of the active ingredients of sAg might contribute to drug development and vaccine design for parasitic or autoimmune diseases." (PMID 29391024, 2018).
autoimmune uveitis (3 papers, 2024). An autoimmune form of uveitis (disease). "The development of autoimmune uveitis is associated with Th cells specific to retinal antigens such as S-antigen/visual arrestin (SAG), interphotoreceptor retinoid-binding protein (IRBP), rhodopsin, phosducin and several other proteins." (PMID 39684616, 2024).
bacteremia (3 papers, 2016 to 2025). "To evaluate if the SAB-0485 and SAB-0495 strains exhibited increased persistence in vivo, we utilized an experimental model of bacteremia in transgenic mice that express the human MHC-II molecule human leukocyte antigen (HLA)-DR4 (herein referred to as DR4-B6 mice) and are sensitive to SAg function." (PMID 39878522, 2025).
hepatitis A (3 papers, 2013 to 2022). "Baseline serum IgG results for measles, mumps, rubella, varicella zoster virus (VZV) & hepatitis A, as well as hepatitis B sAg, cAb and sAb results, were retrieved for 2534 clinic attendees attending in 2018." (PMID 35768790, 2022). "Positive screening results for hepatitis A (IgG), hepatitis B (sAg), and HCV (IgG) had roughly equivalent proportions for both case patients and controls." (PMID 32372751, 2020). "Retrospective viral hepatitis serology on baseline serum samples from both studies revealed in the > five years population (Study-T) around 15% HBV prevalence (HBV sAg positive), among these about 4% with a probable (recent) active hepatitis (IgM anti-HBc positive)." (PMID 23866736, 2013).
lymphoma (3 papers, 2002 to 2023). A malignant (clonal) proliferation of B- lymphocytes or T- lymphocytes which involves the lymph nodes, bone marrow and/or extranodal sites. "It has been described that SAg can induce apoptosis in murine lymphoma T cells in vitro and in vivo." (PMID 37377961, 2023). "In previous reports, we described the capability of SAg to induce apoptosis of murine lymphoma cells in vitro and in vivo, increasing the survival of lymphoma-bearing mice." (PMID 37377961, 2023). "Thus, EBV-triggered ERVK18 SAg expression may contribute to lymphoma by triggering the expansion of self-reactive T cells via stimulating Vβ7 T cells and the subsequent breakdown of host immunity." (PMID 26617584, 2015).
melanoma (3 papers, 2020 to 2025). A malignant, usually aggressive tumor composed of atypical, neoplastic melanocytes. "Key targets of SAG treatment for melanoma are enriched in the phosphatidylinositol 3-kinase/AKT pathway 42, and activating transcription factor-3 inhibits melanoma growth by downregulating the extracellular regulated protein kinase and AKT levels." (PMID 39744474, 2025). "In addition, we validated that respective treatment of LiCl (Wnt/β-catenin activator) or SAG (Hedgehog activator) induced Cyr61 expression in two melanoma cells." (PMID 32732916, 2020). "Furthermore, consistent with the data obtained in melanoma cells, a positive regulation of MEK5 phosphorylation by HH-GLI signalling was observed in NIH/3T3 cells upon SAG treatment." (PMID 34681917, 2021).
Oguchi type 1 disease (3 papers, 2012 to 2022). "Compound heterozygosity of a nonsense p.S25X mutation in exon 2 and a splicing alteration in exon 6 of the SAG gene is the cause of this patient with Oguchi type 1 disease in China." (PMID 35246075, 2022). "In conclusion, we have identified the first nonsense mutation in the SAG gene in a patient with Oguchi type 1 disease in Pakistan." (PMID 22665972, 2012). "Mutations in arrestin gene (SAG, S-antigen; OMIM:181031) were first discovered in Japanese patients (Oguchi disease type 1), later on, mutations involving the rhodopsin kinase gene (GRK1; OMIM:180381) were implicated in European patients (Oguchi disease type 2)." (PMID 35549688, 2022).
retinitis pigmentosa (3 papers, 2013 to 2025). Retinitis pigmentosa (RP) is an inherited retinal dystrophy leading to progressive loss of the photoreceptors and retinal pigment epithelium and resulting in blindness usually after several decades. "Strikingly, eight of the 67 exclusive candidates are associated with retinitis pigmentosa (human orthologues in parentheses): Gnat1 (GNAT1), Rom1a and Rom1b (ROM1), Kfharr-r2 (SAG, ARRESTIN, RP47), Rgra (RGR, RP44), Tbl2 (TBL2), Sec31b (SEC31B) and Glyr1 (GLYR1)." (PMID 34106226, 2021).
autosomal dominant retinitis pigmentosa (2 papers, 2018 to 2024). Autosomal dominant retinitis pigmentosa (RP) is an autosomally dominant inherited retinal dystrophy leading to progressive loss of the photoreceptors and retinal pigment epithelium and resulting in blindness usually after several decades. "Patient five had a clinical diagnosis of posterior polar choroidal annular dystrophy and both Invitae and BG found a likely pathogenic mutations in SAG, which is associated with autosomal dominant retinitis pigmentosa and autosomal recessive Oguchi disease." (PMID 38892829, 2024).
colon carcinoma (2 papers, 2014 to 2020). "In a humanized mouse model of colon cancer, we demonstrate that the scFv5T4::SpeCD203A TTS controls the growth and metastatic potential of an established colon cancer tumor, and that this anti-tumor activity requires both specific targeting by the scFv5T4 moiety, as well as SAg function." (PMID 24736661, 2014).
COVID-19 (2 papers, 2020 to 2022). A disease caused by infection with severe acute respiratory syndrome coronavirus 2. "Moreover, analysis of a cohort of adult COVID-19 patients reveals that those with severe hyperinflammatory disease exhibit skewing of the TCR repertoire consistent with SAg activity." (PMID 32989130, 2020). "Moreover, our analysis of the T cell immune response in COVID-19 patients shows that those with more severe and hyperinflammatory clinical courses exhibit TCRVβ skewing consistent with SAg activity." (PMID 32989130, 2020).
E. coli infection (2 papers, 2021 to 2024). "Strikingly, we also demonstrated the HH signaling agonist SAG protection on mice with meningitic E. coli infection." (PMID 38360663, 2024). "As an extension of this study, we also discussed the potential protection of rTGFβ1 and SAG in mice against meningitic E. coli infection with two routes of administration, prior to-challenge administration and simultaneous administration." (PMID 34281571, 2021).
hepatitis B (2 papers, 2012 to 2020). "An age gradient was found for the presence of hepatitis B infection (both sAg and cAb)." (PMID 22693599, 2012). "Hepatitis B infection (sAg positive) was found in four of the 10 adults with HCV infection, and co-infection with hepatitis B and Schistosoma was found in 2.7% (15/548) of those screened for both conditions." (PMID 22693599, 2012).
myopia (2 papers, 2018 to 2025). "In addition to the novel mutations found in five known myopia genes (ADAMTS18, CSMD1, P3H2, RPGR, and SLC39A5), we also identified pathogenic variants in seven ocular disease genes (ABCA4, CEP290, HSPG2, PCDH15, SAG, SEMA4A, and USH2A) as novel candidate genes." (PMID 30245926, 2018).
ovarian carcinoma (2 papers, 2020 to 2023). A malignant neoplasm originating from the surface ovarian epithelium. "Similar results were observed in ciliated SKOV3 ovarian cancer cells that enrich SMO in response to SAG stimulation but fail to activate GLI1." (PMID 37830570, 2023).
Stroke (2 papers, 2010 to 2021). Sudden impairment of blood flow to a part of the brain due to occlusion or rupture of an artery to the brain. "Another of the NEMO interactors, SAG, has been characterized as a cellular antioxidant whose overexpression markedly reduces cell death following stroke or treatment with apoptosis inducers." (PMID 20098747, 2010). "Both astrocytes-derived TGFβ1 and the hedgehog agonist SAG were previously reported to maintain the vascular and BBB stabilization under stroke or HIV infection." (PMID 34281571, 2021).
viral infections (2 papers, 2015 to 2024). "As the ERVK18 SAg is also known to be activated by the antiviral cytokine IFNα, an inflammatory response following other exogenous virus infections may be sufficient to enhance ERVK18 Sag expression." (PMID 26617584, 2015). "Thus, SAG induces a significant increase in NK cells, characterized as lymphocytes of the innate immune system that play a pivotal role in the defense against malignancies and viral infections." (PMID 38667291, 2024).
Anxiety (1 paper, 2017). Intense feelings of nervousness, tension, or panic often arise in response to interpersonal stresses. "Our results defined the anti-anxiety effect and interpret the mechanism of SAG." (PMID 28800105, 2017).
atopic dermatitis (1 paper, 2021). "Most atopic dermatitis isolates in this study coproduced TSST-1, and thus, this SAg’s expression could be upregulated once the skin isolate reaches the vaginal mucosa, enabling the strain to cause TSS." (PMID 33504664, 2021).
cervical carcinoma (1 paper, 2021). A carcinoma arising from either the exocervical squamous epithelium or the endocervical glandular epithelium.
chronic myelogenous leukemia (1 paper, 2019). "The top scoring candidates included Nilotinib and Imatinib, two protein kinase inhibitors used to treat chronic myelogenous leukemia; their docking scores were comparable to those of the known SMO modulators Vismodegib and SAG." (PMID 31539380, 2019).
coccidiosis (1 paper, 2011). A parasitic infection caused by Coccidia. "SAG gene repertoires and expression profiles are yet to be determined for E. acervulina and E. maxima, causes of malabsorptive coccidiosis, and may be distinct from that observed for E. tenella." (PMID 21980402, 2011).
cyst (1 paper, 2018). A sac-like closed membranous structure that may be empty or contain fluid or amorphous material. "SAG together with FSK and EGF resulted in similar cyst number and size as FSK and EGF treatment, suggesting SAG does not exacerbate FSK and EGF-induced cyst growth." (PMID 29563577, 2018).
Down syndrome (1 paper, 2017). "Under the assumption that reduced HH signalling causes several defects in Down syndrome patients, a mouse model of Down syndrome was treated with SAG." (PMID 29615572, 2017).
endometriosis (1 paper, 2023). The growth of functional endometrial tissue in anatomic sites outside the uterine body. "Essentially, the activation of PGR downstream pathways with SAG rescued the abnormal epithelial proliferation in Cfp1d/d uterus and suppressed the ectopic growth of Cfp1d/d uterine lesions with P4 resistance in the endometriosis model." (PMID 37270588, 2023). "When SAG was administered to rescue P4 resistance and/or insensitivity in Cfp1d/d ectopic uterine lesions, P4 suppressed the size of Cfp1d/d ectopic lesions in the endometriosis model, suggesting that CFP1 is required for proper P4 responses to suppress ectopic growth of uterine tissues in mice." (PMID 37270588, 2023).
gastric cancer (1 paper, 2016). A primary or metastatic malignant neoplasm involving the stomach. "Compared to the levels in immortalized “normal” human gastric epithelial GES-1 cells, RBX1 and SAG were over-expressed in most of gastric cancer cell lines tested, with the highest expression seen in MKN-45, AGS and SGC-7901 cells." (PMID 27063292, 2016). "Taken together, these results showed that two RING components of CRL1, RBX1 and SAG are over-expressed in a number of gastric cancer cell lines and that MLN4924 effectively inactivates cullin neddylation." (PMID 27063292, 2016). "Given that there is no previous study showing any potential correlation between RBX1/SAG expression and MLN4924 sensitivity, we chose two gastric cancer lines, AGS and SGC-7901 with an over-expressed RBX1 and SAG for this study." (PMID 27063292, 2016). "To further investigate the role of CRL1/SCF in gastric cancer, we first determined the expression levels of three CRL1/SCF E3 components, RBX1, SAG/RBX2 and cullin-1 in several gastric cancer cell lines." (PMID 27063292, 2016).
herpesvirus infections (1 paper, 2024). "With the combined effects of sEV, Epstein–Barr nuclear antigen 1(EBNA1)–DNA complexes, EBNA1–IgG–complement immune complexes, HERV-W/K sAg elements, and the early reactivation induced by other herpesvirus infections, the inflammatory cascade continuously amplifies, ultimately resulting in MS onset." (PMID 39397863, 2024).
influenza (1 paper, 2020). An acute viral infection of the respiratory tract, occurring in isolated cases, in epidemics, or in pandemics; it is caused by serologically different strains of viruses (influenzaviruses) designated A, B, and C, has a 3-day incubation period, and usually lasts for 3 to 10 days. "It will be interesting to assess whether SAg-expanded IAV-specific TCD8 will be equally likely, less likely or more likely to undergo mutations, which may potentially affect their significance in the context of influenza following exposure to the toxins or bacterial pathogens that release them." (PMID 32433711, 2020).
leukemia (1 paper, 2017). A malignant (clonal) hematologic disorder, involving hematopoietic stem cells and characterized by the presence of primitive or atypical myeloid or lymphoid cells in the bone marrow and the blood. "Impede SAG activity by blocking its cullin neddylation which can sensitize leukemia cell lines HL-60 and KG-1 to retinoic acid." (PMID 28579943, 2017). "MLN4924, an inhibitor of E3 ubiquitin ligase activity of SAG-SCF, has shown a promising effect in sensitizing leukemia cells toward the effects of retinoic acid." (PMID 28579943, 2017).
Lowe syndrome (1 paper, 2020). "Similar to Inpp5e-null cells, fibroblasts from the Lowe syndrome mouse model exhibit reduced SAG-stimulated SMO ciliary localisation." (PMID 32970140, 2020).
malaria (1 paper, 2025). Malaria is a serious and sometimes fatal disease caused by a parasite that commonly infects a certain type of mosquito which feeds on humans. "In addition, genes encoding SG1 family proteins, such as SAG (Saglin), TRIO (triple functional domain protein) and GILT (mosquito gamma-interferon-inducible lysosomal thiol reductase), that are associated with infection by malaria parasites also showed a cyclic profile." (PMID 40164831, 2025).
mastitis (1 paper, 2018). Inflammation of breast tissue during lactation or postpartum due to an obstructed duct or infection. "However, an understanding of the diversity and distribution of SAg genes among bovine Staphylococcus aureus strains and their role in the pathogenesis of mastitis is lacking." (PMID 30201699, 2018).
non-small cell lung carcinoma (1 paper, 2016). A group of at least three distinct histological types of lung cancer, including non-small cell squamous cell carcinoma, adenocarcinoma, and large cell carcinoma. "Our recent study showed that both RBX1 and SAG/RBX2 are overexpressed in human non-small cell lung carcinomas." (PMID 27955654, 2016).